PYY (peptide YY)
Diseases named in the same sentence as PYY in open-access papers (continued):
Sharing a sentence is not in itself a finding about the gene and the disease.
Obesity (continued). "It has been suggested that the lower postprandial PYY concentrations measured in obesity would result in increased food intake in order to achieve the same degree of fullness as that seen normal weight individuals." (PMID 36416279, 2023). "The quantitative analysis demonstrated that postprandial total PYY concentrations were statistically significantly lower in individuals with obesity compared with controls." (PMID 36416279, 2023). "Further, previous studies have shown that females with AN have elevated PYY levels compared to normal weight individuals or those with obesity and demonstrated a strong inverse correlation between PYY and BMD." (PMID 37393263, 2023). "Herein, we utilize a validated, ultrasensitive, and quantitative LC‐MS/MS assay for PYY1‐36 and PYY3‐36 to investigate the postprandial secretion of PYY peptides in obesity and the changes after bariatric surgery." (PMID 36345253, 2023). "Since the male PE offspring showed an increased postnatal weight gain, a subset of metabolic active obesity-related hormones, such as Ghrelin, Glucagon, Insulin, Leptin and PYY, were analyzed." (PMID 37108049, 2023). "Mechanisms underlying long-term sustained weight loss and glycemic normalization after obesity surgery include changes in gut hormone levels, including glucagon-like peptide 1 (GLP-1) and peptide YY (PYY)." (PMID 37308546, 2023). "In the present study, we sought to identify agents to induce both endogenous GLP-1 and PYY secretion, thereby providing a safe and alternative strategy for obesity and T2D management." (PMID 36386896, 2022). "As will be understood, it is difficult to assign a causal role for the development of obesity to the decreased secretion of GLP-1 and PYY." (PMID 35990325, 2022). "In conclusion, we found for the first time that EA is a novel agent with potent anti-diabetic and anti-obesity effects in mouse models of obesity and T2D, which were associated with increased secretion of GLP-1 and PYY." (PMID 36386896, 2022). "An increase of colonic propionate stimulates GLP-1 and PYY release in mice and rats, and reduces weight and obesity-related fatty liver disease in diet-induced obese mice." (PMID 35629921, 2022). "The lower secretion in obese individuals has been confirmed in many studies, and combined with the finding that also PYY levels are reduced in obesity, supports the notion of an impairment of L-cell performance in obesity." (PMID 35990325, 2022). "While PYY is known to reduce appetite and energy intake, delay gastric emptying, and promote insulin secretion, its relationship with obesity and IR remains controversial." (PMID 35334929, 2022). "Unfortunately, there are no longitudinal studies to provide information about the time when, in the development of obesity, the impaired secretion of PYY and GLP-1 sets in." (PMID 35990325, 2022). "There is general agreement that the secretion of intestinal proglucagon derived appetite inhibitory hormones, GLP-1, PYY, and oxyntomodulin is impaired in obesity." (PMID 35990325, 2022). "Alterations in gut hormone secretion have been associated with the pathogenesis of obesity, and attenuated responses of GIP, GLP-1, and PYY have been reported both in humans and in rodent models." (PMID 35600607, 2022). "In contrast, PYY infusion reduces hunger and caloric intake in obese and lean subjects, making exogenous PYY a potential therapy for obesity." (PMID 35276299, 2022). "SCFAs, primarily butyrate, propionate and acetate, can stimulate the release of the anorexigenic peptides including Peptide YY (PYY), amylin and Glucagon-like peptide 1 (GLP-1) and inhibit obesity caused by a high-fat diet." (PMID 34375351, 2021). "The inhibition of appetite is further supported by the strong upregulation of peptide YY at a local level, which in mammals has been shown to inhibit appetite and reduce obesity." (PMID 33777043, 2021).
Obesity (continued). "With an increase in food intake and the development of obesity, not only the levels of PYY in the serum are reduced, but also the magnitude in increase upon ingestion of food is significantly lower." (PMID 33749879, 2021). "Blood levels of PYY rise at the time of completion of a meal, a baseline PYY concentration during fasting is lower in individuals with obesity, and peripheral injections of this hormone promote a marked reduction in the amount of consumed food." (PMID 33808819, 2021). "The purpose of the study was to assess the serum levels of NPY and PYY in adolescents with anorexia nervosa (AN) or obesity (OB), as well as in a healthy control group (CG)." (PMID 33670342, 2021). "Polyphenol-enriched beverage that made from turmeric increases the postprandial concentration of anorexigenic hormone, peptide tyrosine tyrosine (PYY) in the healthy individuals, suggesting a potential anti-obesity action of turmeric polyphenols." (PMID 33572808, 2021). "PYY levels are lower in obese adults and the elevation of PYY seen after a meal in lean subjects is blunted in obesity." (PMID 34948466, 2021). "On the other hand, different studies have shown the relevance of PYY in the etiology of obesity and type 2 diabetes." (PMID 34206176, 2021). "Inulin-type carbohydrates increase the density of PYY-producing cells, thus showing its role in reducing appetite and food intake and enhancing obesity treatment." (PMID 34684121, 2021). "This has important clinical and safety implications for the continuing development of PYY analogs for the treatment of obesity." (PMID 31628465, 2020). "This study examined further the impacts of A. muciniphila in the HFD-fed animals on the colonic gene expression of GLP-1 and PYY, which are the gut hormones with appetite suppressing and anti-diabetic plus anti-obesity properties, respectively." (PMID 32937828, 2020). "Previously, we found that oat β-glucans increase satiety by activation of the gut-hypothalamic (PYY-NPY) axis in diet-induced obesity in mice." (PMID 33008466, 2020). "Further research employing normal-weight controls as well as the consideration of hormonal status or menstrual cycle phase are required to better understand the role of NPY, PYY and PP in the pathophysiology of obesity and the emotional response to stress." (PMID 33192409, 2020). "Obesity is accompanied by altered secretions of leptin, ghrelin, GLP-1, PYY, and CCK, which are in turn associated with accelerated weight gain." (PMID 32756479, 2020). "PYY analogs combined with glucagon-like peptide-1 (GLP-1) agonists are currently under development for the treatment of obesity." (PMID 32121443, 2020). "There are already several gut peptide mimetics such as GLP-1, DDP IV inhibitors, CCK antagonists, PYY, PP in clinical trials for obesity and diabetes." (PMID 30837951, 2019). "An attenuated postprandial PYY response in young people with obesity compared with that in those of healthy weight has been shown from a recent meta-analysis of a small number of studies." (PMID 30764560, 2019). "There is impairment of satiety cues in individuals with overweight or obesity, such as low production of satiety hormone PYY, relative to subjects with normal weight." (PMID 31706311, 2019). "A number of total PYY results were below a detectable level (<13.7 pg/mL), resulting in a PYY sample size of n = 5 adolescents with obesity and n = 5 of healthy weight adolescents." (PMID 30764560, 2019). "As a significant material of intestinal endocrine cells, PYY (peptide YY) acts in the regulation of obesity." (PMID 31195699, 2019). "It was also later discovered that combined administration of davalintide, an amylinomimetic, and a peptide YY (PYY) is advantageous in treating obesity." (PMID 30834248, 2019). "For example, antibiotic treatment has been shown to decrease PYY levels, an effect accompanied by increased food intake and increase in abundance of obesity dominant bacteria." (PMID 30837951, 2019).
Obesity (continued). "As PYY analogs are under development for treatment of obesity, we aimed to clarify the relationship between PYY and bone mass." (PMID 31306808, 2019). "In female Sprague–Dawley rats, a high-fat/sucrose diet-induced obesity group had higher blood glucose, plasma insulin, and leptin concentrations and lower peptide-YY (PYY) levels than the lean group." (PMID 29208770, 2018). "Other studies have also demonstrated that PYY and PP concentrations are unchanged in the hours after exercise in individuals with overweight or obesity." (PMID 30131457, 2018). "Appetite control is important in addressing the problem of obesity and is represented by the levels of PYY and ghrelin." (PMID 30390699, 2018). "Our study showed that women with PCOS had a significant decrease of serotonin, ghrelin, and PYY level compared with controls, and obesity enhanced the difference of serotonin and ghrelin in PCOS." (PMID 28293234, 2017). "Studies have shown that the concentration of meal-induced PYY are lower in obese individuals, indicating that food items which increase levels of PYY are important in the prevention of obesity." (PMID 26990559, 2016). "Increased intake of dietary protein is associated with increased release of the gut satiety hormone PYY in humans and mice, while exogenous PYY reverses the hyperphagic obesity seen in PYY-knockout mice." (PMID 27224646, 2016). "Some studies carried out in recent years also emphasize the potential role of gut hormones in the development of obesity (especially ghrelin and peptide YY)." (PMID 27212946, 2016). "Retarding gastric emptying and acting as satiety factors of both GLP-1 and PYY have physiologically significant functions of relevance to obesity and T2DM." (PMID 27069493, 2016). "While investigating other hormones that were related to metabolism and obesity, increased PYY serum levels after HFD were observed in adult offspring of maternal swimmers, which is a potential indicator for inhibitory appetite effects." (PMID 26690877, 2015). "The CaSR seems to promote the secretion of GLP-1 and PYY, and has thus been identified as a potential therapeutic target in the treatment of diabetes and obesity." (PMID 26258126, 2015). "An N-terminally degraded metabolite, PYY3–36, has anorexigenic effects, which makes the PYY system a target for obesity treatment." (PMID 26197931, 2015). "Obesity was also associated with increased levels of leptin, insulin, glucagon, GLP-1, PYY, and C-peptide in overweight and obese chimpanzees." (PMID 25309773, 2014). "Studies conducted on a small sample of humans showed that endogenous PYY concentrations were lower in obese subjects and inversely correlated with obesity-related phenotypes." (PMID 24743402, 2014). "The initial investigations involving PYY, conducted in rodents, revealed that a diet-induced obesity state decreased PYY concentrations." (PMID 24743402, 2014). "We previously reported that JTT-130 suppressed cumulative food intake along with the increased GLP-1 and PYY levels and ameliorated diet-induced obesity and glucose intolerance in Sprague-Dawley rats fed a 35% fat diet." (PMID 24895641, 2014). "We demonstrated that obesity is associated with increased levels of C-peptide, leptin, insulin, GLP-1, PYY, and glucagon." (PMID 25309773, 2014). "Individuals with obesity display an attenuated meal-stimulated PYY response and require a greater caloric load to achieve a postprandial PYY concentration similar to that seen in lean controls." (PMID 24250335, 2013). "GLP-1 and PYY are considered anti-diabetic and anti-obesity hormones, and GLP-1-based therapies are currently used as a novel treatment for type 2 diabetes." (PMID 23577078, 2013). "Increased levels of leptin and reduced levels of PYY are features of obesity with peripheral insulin resistance." (PMID 25035815, 2013). "Similar to GLP-1, PYY levels are low in obesity and at least a blunted response to a meal has been described in T2D." (PMID 22619730, 2012).
Obesity (continued). "Rodents and humans with reduced PYY levels in response to food intake tend toward obesity, for example." (PMID 17530919, 2007). "The effect of this hormone was also studied in obese children, where there is a reciprocal relationship between obesity and PYY." (PMID 17530919, 2007). "Given that PYY suppresses appetite, its lower concentrations in individuals with obesity may contribute to increased food intake and weight gain." (PMID 41575482, 2026). "In individuals with a combination of obesity and T2DM/IGT, the PYY response to fat intake was also diminished compared to the control group; however, in this case, the coexistence of severe obesity may have influenced the results." (PMID 41575482, 2026). "The greater levels of adiposity in the present study could be a contributing factor as the circulating total PYY response to acute exercise is reported to be trivial or blunted in populations with overweight and obesity." (PMID 40425789, 2025). "This suggests that L. plantarum ST‐III may exert its anti‐obesity effects through mechanisms beyond simple caloric restriction, such as the modulation of gut hormone secretion (e.g., PYY) and the enhancement of intestinal barrier integrity." (PMID 40772021, 2025). "Animal experiments found that inulin could stimulate the production of SCFAs in wild-type or FFAR2-/- mice, drive an increase in the number of cells that secrete PYY, increase the release of PYY, and then suppress appetite to control obesity." (PMID 40697558, 2025). "PYY exhibits anti-inflammatory properties in WAT by downregulating pro-inflammatory factors such as NF-κB and IL-6 in obese mice, thereby mitigating the development of metabolic diseases associated with obesity." (PMID 40723884, 2025). "In addition to these metabolic and lipid-related factors, alterations in gastrointestinal hormone secretion, such as GLP-1, PYY, and ghrelin, in obesity and metabolic syndrome also contribute to the complex mechanisms leading to cholesterol supersaturation." (PMID 40370800, 2025). "It is, accordingly, important to determine whether the effects of calcium and Trp to stimulate CCK, GLP-1, and PYY secretion and pyloric pressures and suppress energy intake are maintained in individuals with obesity." (PMID 39785828, 2025). "Diminished postprandial PYY responses have been observed in people with obesity and T2D." (PMID 41228539, 2025). "Therefore, increased knowledge of the different PYY functions have the potential to expand its therapeutic scope beyond treatment of diabetes and obesity." (PMID 41048045, 2025). "Conversely, in early-stage or obesity-driven T2D characterized by hyperphagia and rapid gastric emptying, PYY may complement existing incretin therapy through appetite control and improved insulin sensitivity at peripheral sites." (PMID 41228539, 2025). "Exercise-related responses may differ according to adiposity status with individuals with overweight/obesity experiencing a greater elevation in total GLP-1 but a blunted increase in total PYY in response to acute exercise when compared to lean individuals." (PMID 40425789, 2025). "The observed results suggest that cord blood appetite hormones (PP, PYY, and leptin) might play a role in the early-life development of obesity." (PMID 41196593, 2025). "A similar suppression of postprandial PYY was noted in Black females with obesity." (PMID 41043686, 2025). "In people with obesity or type 2 diabetes, secretion of PYY after meals is frequently diminished, which may account for the observed acceleration of gastric emptying and increased blood glucose variability." (PMID 41228539, 2025). "Notably, participants with normal body weight exhibited higher PYY concentrations than those with obesity." (PMID 40806130, 2025).
Obesity (continued). "The elevated gut SCFAs, especially propionic acid, were accompanied by up-regulation of GPR41 and GPR43 and a parallel rise in the obesity-related hormones GLP-1 and PYY; a direct causal chain remains to be proven, mitigating the obesity and its associated metabolic disorders." (PMID 41356823, 2025). "K cells and L cells, the most widely studied EECs, are the targets of antidiabetic therapies because of their secretion of gut peptides [e.g., gastric inhibitory peptide (GIP), glucagon-like peptide-1 (GLP-1), and peptide YY (PYY)] with anti-obesity and/or antidiabetic action." (PMID 39671480, 2024). "An inverse correlation is observed between plasma PYY and BMD in populations with weight gain and obesity (decreased PYY and increased BMD) and in weight loss scenarios (increased PYY and decreased BMD), as observed in patients with anorexia and amenorrheic athletes." (PMID 39054499, 2024). "However, its role in the development of obesity remains controversial and unclear, as the mechanisms of PYY action have been understudied and underanalyzed." (PMID 39408213, 2024). "In EECs, RGS, specifically RGS9, may modulate the secretion of nutrient-stimulated GPCR-mediated GLP-1 and PYY from gut L cells, and this system may serve as a potential target for the pharmacological treatment of obesity." (PMID 39142076, 2024). "In fact, PYY-1-knockout mice manifest obesity, which is reversed by exogenous PYY-1 administration." (PMID 36675084, 2023). "Interestingly, a similar systematic review and meta‐analysis previously conducted in children reported the same results, with an attenuated postprandial total ghrelin and total PYY response in children with obesity, despite large heterogeneity." (PMID 36416279, 2023). "Several studies have shown that PYY levels are altered in individuals with obesity." (PMID 37600709, 2023). "The role of PYY in treating obesity has been investigated in several clinical studies." (PMID 37600709, 2023). "The obesity susceptibility in PYY gene has not been confirmed in Online Mendelian Inheritance in Man (OMIM)." (PMID 37953234, 2023). "Interestingly, the responses of PYY and ghrelin are blunted when obesity and insulin resistance occur." (PMID 37159195, 2023). "Additionally, factors related to adipose tissue, including resistin, peroxisome proliferator-activated receptor gamma, and peptide YY, are believed to participate in the detrimental influence of obesity on bone health." (PMID 37571429, 2023). "Fourth, breastfeeding has been associated with increased levels of adipokines such as ghrelin and peptide YY and these cytokines could reduce risks of diabetes and obesity." (PMID 35045125, 2022). "Furthermore, individuals with obesity have reduced fasting levels of PYY and GLP-1 and blunted meal-stimulated levels of these anorectic peptides, in addition to an attenuated satiety-promoting effect of CCK, leptin resistance, and IR." (PMID 35334929, 2022). "However, the evidence in the literature with respect to the involvement of PYY in the development of obesity is controversial and unclear." (PMID 36355134, 2022). "This study explored the effect of three different modes of resistance training on appetite hormones [leptin, ghrelin, cholecystokinin (CCK), glucagon-like peptide-1 (GLP-1), and peptide tyrosine–tyrosine (PYY)], cardiometabolic and anthropometric measures in males with obesity." (PMID 35264977, 2022). "It is of course important to explore whether the lower secretion of PYY and GLP-1 in obesity is a consequence or a cause of the condition." (PMID 35990325, 2022). "The accompanied change in food preference in obesity away from diets high in fiber could be one of the contributors to this decrease in PYY levels." (PMID 33749879, 2021). "If the treatment period had been extended, potentially even greater losses may have been reached, thus confirming the great efficacy when combining GLP-1 and PYY for obesity treatment." (PMID 34707178, 2021).